POT1 (protection of telomeres 1)
Diseases named in the same sentence as POT1 in open-access papers (continued):
Sharing a sentence is not in itself a finding about the gene and the disease.
pulmonary fibrosis (5 papers, 2019 to 2025). Chronic progressive interstitial lung disorder characterized by the replacement of the lung tissue by connective tissue, leading to progressive dyspnea, respiratory failure, or right heart failure. "Previous studies have implicated germline variants in POT1 in specific telomere syndromes, such as Coats plus and idiopathic pulmonary fibrosis." (PMID 39198715, 2024). "Here we report the first known family with pulmonary fibrosis carrying a heterozygous POT1 mutation." (PMID 35420632, 2022). "This study reports the first known family with pulmonary fibrosis carrying a heterozygous POT1 mutation." (PMID 35420632, 2022). "Exonic sequencing identified a family with idiopathic pulmonary fibrosis (IPF) containing a previously unreported heterozygous mutation in POT1 p.(L259S)." (PMID 35420632, 2022). "Two of the brothers carry exclusively the POT1 mutation and present longer telomeres (25–50% of the population) although one of them has developed pulmonary fibrosis." (PMID 30995915, 2019). "Genetic analysis on our 36-gene pulmonary fibrosis gene panel revealed a heterozygous variant in POT1: c.776T>C; p.(Leu259Ser) and no abnormalities in the other 35 genes tested." (PMID 35420632, 2022).
acute myeloid leukemia (4 papers, 2015 to 2025). Acute myeloid leukemia (AML) is a group of neoplasms arising from precursor cells committed to the myeloid cell-line differentiation. "Here, we present the novel finding of a germline stop-gain variant (p.Q199*) in the shelterin complex gene POT1, which was identified in a child with acute myeloid leukemia." (PMID 34769003, 2021). "Here, we present a novel loss of function stop-gain mutation in POT1 (p.Q199*) in a boy with acute myeloid leukemia (AML)." (PMID 34769003, 2021). "Here we analyzed TERT and protection of telomeres 1 gene (POT1) mutations, and four different TERT SNVs in 226 acute myeloid leukemia (AML) patients and 806 healthy individuals in a case referent design, where also overall survival was assessed." (PMID 26298771, 2015). "TERF1, TERF2, TINF2, and POT1 are significantly expressed in testicular, Acute Myeloid Leukemia (AML), prostate and breast as well as renal cancers, respectively." (PMID 39578854, 2024).
multiple myeloma (4 papers, 2019 to 2024). "An exome analysis found three POT1 variants in as many multiple myeloma patients out of 128 patients: c.458T>A, c.1594G>C, and c.547-1G>A." (PMID 38254993, 2024). "For instance, in multiple myeloma, POT1 mRNA levels have been associated with clinical stage and patient mortality." (PMID 32987645, 2020).
non-small cell lung carcinoma (4 papers, 2020 to 2025). A group of at least three distinct histological types of lung cancer, including non-small cell squamous cell carcinoma, adenocarcinoma, and large cell carcinoma. "Notably, a pan-cancer study on 62,368 tumors revealed that deleterious POT1 variants are present in approximately 5% of non-small cell lung cancers." (PMID 39156708, 2024).
bone marrow failure (3 papers, 2016 to 2025). "In addition, there are recent reports suggesting that specific POT1 variants may be associated with a different condition, dyskeratosis congenita, an inherited bone marrow failure condition characterised by specific mucocutaneous features." (PMID 40350252, 2025). "Heterozygous carriage of TPP1 variants are associated with dyskeratosis congenita, bone marrow failure, and IPF, while homozygous carriage of a POT1 variant has been implicated in CP." (PMID 35420632, 2022). "Unlike POT1, mutated TIN2 and TPP1 have not been observed in tumors, but germline mutations of these genes have been reported in human genetic diseases leading to bone-marrow failure." (PMID 27486974, 2016).
brain tumours (3 papers, 2018 to 2025). "Nonetheless, two cases of brain tumours and a case of lymphoproliferative syndrome were identified, which have not been described before in association with this specific POT1 PV, but are known to be related to POT1-TPD, reinforcing the recognised disease spectrum of POT1 mutations." (PMID 38839987, 2024). "Associations have been suggested for LFS-associated brain tumors with nonsense PVs in CASP9 (caspase-9), for a POT1 (protection of telomeres 1) missense variant with cardiac and breast angiosarcomas, and for CDKN2A PVs with hereditary sarcoma cases." (PMID 30086788, 2018). "In these three families, it was possible to observe the typical POT1-TPD: two cases of CM, two cases of cardiac angiosarcoma, one case of CLL and two cases of brain tumours, in total." (PMID 38839987, 2024).
childhood cancer (3 papers, 2020 to 2024). "Using a functional variant approach, we identified and confirmed an association between a low frequency intronic regulatory POT1 variant and thyroid subsequent malignant neoplasm in survivors of childhood cancer." (PMID 32040538, 2020). "A study on participants of the Childhood Cancer Survivor Study identified an association between a low-frequency intronic regulatory variant in POT1 and the risk for thyroid subsequent malignant neoplasm in the survivors and provided evidence that the variant may be related to longer TL." (PMID 32492864, 2020). "Using an approach that mapped functional variants to candidate genes, we identified an association between a low frequency intronic regulatory variant in POT1 and risk for thyroid SMN in survivors of childhood cancer." (PMID 32040538, 2020).
differentiated thyroid carcinoma (3 papers, 2022 to 2025). Differentiated thyroid carcinoma (DTC), also known as papillary or follicular thyroid carcinoma, is a slow-growing malignancy usually presenting in adults as an asymptomatic thyroid mass. "However, it is known that several other hereditary syndromes are associated with differentiated thyroid cancer, so further studies are needed regarding POT1 mutations and the risk of PTC." (PMID 38839987, 2024). "Colorectal and differentiated thyroid cancer have also been proposed as part of POT1-TPDS." (PMID 40350252, 2025).
hepatocellular carcinoma (3 papers, 2015 to 2019). A malignant tumor that arises from hepatocytes. "In hepatocellular carcinoma (HCC) the POT1 rs7784168 SNP is significantly associated with a decreased risk of major vessel invasion and postoperative recurrence." (PMID 26143636, 2015). "Additionally, POT1 and RAP1 expression appeared deregulated in hepatocellular carcinoma (HCC)." (PMID 30654820, 2019).
Li-fraumeni-like syndrome (3 papers, 2020 to 2025). "In particular, we demonstrated that families with Li-Fraumeni Like Syndrome carrying POT1 mutations showed increased incidence of different tumor types including the rare cardiac angiosarcoma (CAS)." (PMID 35727838, 2022). "POT1 has specifically been associated with Li-Fraumeni-like syndrome." (PMID 41301029, 2025).
lung adenocarcinoma (3 papers, 2022 to 2024). A carcinoma that arises from the lung and is characterized by the presence of malignant glandular epithelial cells. "Notably, GIST and lung adenocarcinoma were not previously reported in association with the POT1 germline variant." (PMID 39156708, 2024). "Here, we report a unique case of a male patient diagnosed with POT1-TPD, subsequently found to be manifesting gastrointestinal stromal tumor (GIST) and lung adenocarcinoma." (PMID 39156708, 2024).
lymphoid neoplasm (3 papers, 2021 to 2025). A neoplasm composed of a lymphocytic cell population which is usually malignant (clonal) by molecular genetic and/or immunophenotypic analysis. "Finally, the possible contribution of germline mutations, including DDX41, RUNX1, ETV6, ANKRD26, and POT1, which have been associated with the occurrence of both myeloid and lymphoid neoplasms, is an intriguing point to be explored in future studies." (PMID 34733777, 2021).
ovarian carcinoma (3 papers, 2017 to 2025). A malignant neoplasm originating from the surface ovarian epithelium. "However, whether reduced POT1 expression causes cell apoptosis or promotes cell proliferation and exacerbates malignancy in ovarian cancer is unclear." (PMID 29546066, 2018). "In this study, we showed for the first time that reduced POT1 expression in ovarian cancer SK-OV3 cells immediately resulted in temporary inhibition of proliferation and tumorigenicity but ultimately led to enhanced proliferation and tumorigenicity." (PMID 29546066, 2018). "Here, we investigated the impact of POT1 knockdown (POT1-KD) on in vitro cell proliferation, tumorigenesis, and histone deacetylase inhibitor (HDACi) response in human ovarian cancer-derived SK-OV3 cells." (PMID 29546066, 2018). "In this study, we aimed to investigate the effects of POT1 gene expression knockdown on in vitro cell proliferation and tumorigenesis in human ovarian cancer SK-OV3 cells and to explore the role of c-Myc in these phenomena." (PMID 29546066, 2018). "Thus, decreased POT1 expression is likely a catastrophic event in ovarian cancer progression because it results in c-Myc dysregulation." (PMID 29546066, 2018). "We also investigated whether JNJ-26481585 can effectively treat human ovarian cancer POT1-KD SK-OV3 cells and elucidated the mechanism by which JNJ-26481585 exerts its effects." (PMID 29546066, 2018). "Previous studies have suggested that the inhibition of POT1 expression is associated with apoptosis or proliferation of tumor cells; however, the role of POT1 in human ovarian cancer remains unclear." (PMID 29546066, 2018). "However, the role of POT1 in the malignant progression of ovarian cancer is unclear." (PMID 29546066, 2018). "However, the way in which c-Myc influences cell proliferation and tumorigenicity in human ovarian cancer POT1-KD cells is unknown." (PMID 29546066, 2018). "In summary, our findings indicated that POT1 knockdown resulted in a time-dependent effect on proliferation, tumorigenicity, and HDACi response in SK-OV3 ovarian cancer cells via the regulation of c-Myc." (PMID 29546066, 2018). "Human ovarian cancer SK-OV3 cells were infected with POT1 lenti-shRNA or nonspecific shRNA, the latter of which served as a negative control." (PMID 29546066, 2018). "The roles of protection of telomeres 1 (POT1) in human ovarian cancer have not been fully elucidated." (PMID 29546066, 2018). "JNJ-26481585 is a promising agent that may be used to arrest ovarian cancer development, and c-Myc is the putative therapeutic target and should be a response predictor for JNJ-26481585 treatment independently of POT1 status." (PMID 29546066, 2018).
T cell lymphoma (3 papers, 2020 to 2025).
telomere syndrome (3 papers, 2021 to 2024). Accelerated aging syndromes often caused by inheritable gene mutations resulting in decreased telomere lengths. "Interestingly, even though AML is commonly associated with short telomere syndromes (STS), our data support an opposite scenario of telomere elongation mediated by POT1 p.Q199* in our patient." (PMID 34769003, 2021).
bipolar disorder (2 papers, 2024 to 2025). A disorder of the brain that causes unusual shifts in mood, energy, activity levels and the ability to carry out day-to-day tasks. "Another study analyzed the expression of 29 genes involved in telomere homeostasis and aging and observed a downregulation of POT1 in individuals with bipolar disorder with shorter telomeres, compared to age-matched cases with normal telomere length." (PMID 40887790, 2025).
breast angiosarcoma (2 papers, 2018 to 2022). A malignant vascular neoplasm arising from the breast.
cardiac sarcoma (2 papers, 2020 to 2022). "Although additional POT1 variants have been found in cardiac angiosarcomas and cardiac sarcomas, in silico studies predict that these variants are affecting the POT1 function in a similar way than the p.R117C mutation studied here." (PMID 35727838, 2022).
chronic lymphoid leukemia (2 papers, 2015 to 2017). "POT1-mutated chronic lymphoid leukemia (CLL) cells have numerous telomeric and chromosomal abnormalities that implicate the causative influence of the POT1 mutations for malignant CLL cells." (PMID 28404540, 2017). "Ramasay and collaborators found twelve somatic mutations (5%) in POT1 of chronic lymphoid leukemia (CLL) cases, nine detected in the N-terminal OB domain for POT1 and three mutations leading to a truncated protein." (PMID 26143636, 2015).
Coats plus syndrome (2 papers, 2024 to 2025). "Notably, the authors mention several genes involved in DC in their introduction but omit POT1, which is primarily associated with Coats plus syndrome, even though they describe the molecular characterization of pathogenic POT1 variants in DC/DCL cases." (PMID 39198716, 2024).
cutaneous T cell lymphoma (2 papers, 2020 to 2023). "The Denchi and Sfeir labs showed that Pot1a loss in mouse thymocytes increased telomere fragility, and that expression of POT1 mutants associated with cutaneous T cell lymphoma in human and mouse cells impaired POT1 function and increased telomere fragility." (PMID 36833275, 2023). "Somatic mutations in POT1 have also been found in CLL as well as in cutaneous T-cell lymphomas (CTCL) where telomere abnormalities and genomic instability were also observed further supporting its role in malignancy." (PMID 32674474, 2020).
dementia (2 papers, 2022 to 2023). Loss of intellectual abilities interfering with an individual's social and occupational functions. "These loci are associated with several dementia-related genes, including PON1, AP2A2, MAGI2, POT1, ITGAX, PACSIN1, SLC2A8, and EIF4E." (PMID 35299244, 2022).
glioblastoma (2 papers, 2019 to 2024). The most malignant astrocytic tumor (WHO grade IV). "The individual III.16, besides having a glioblastoma had a negative test for the POT1 familiar variant." (PMID 38839987, 2024). "Surprisingly, one case of glioblastoma was not related with the familial POT1 mutation (III.16), and was thus a phenocopy." (PMID 38839987, 2024).
myeloid malignancies (2 papers, 2021 to 2022). "Taken together, our data highlight a potential role of POT1 germline deregulation in the context of predisposition to myeloid malignancies in childhood, which is mediated through telomere elongation." (PMID 34769003, 2021). "The clinical phenotype of the boy harboring the germline stop-gain POT1 variant suggests a link between POT1 p.Q199* and susceptibility to myeloid malignancies with 7q loss." (PMID 34769003, 2021).
thyroid (2 papers, 2020). "The minor allele at Protection of Telomeres-1 (POT1) rs58722976 was associated with increased risk for thyroid subsequent malignant neoplasm (adjusted HR = 6.1, 95% CI: 2.4, 15.5, P = 0.0001; Fisher’s exact P = 0.001)." (PMID 32040538, 2020).
thyroid neoplasms (2 papers, 2021). "POT1 variants are possible biomarkers of secondary thyroid tumors." (PMID 34722258, 2021).
abdominal aortic aneurysm (1 paper, 2018). Enlargement and ballooning of the vessel that supplies arterial blood to the abdomen, pelvis and legs. "Among the miRNAs inversely correlating with POT1, miR-362 has been linked to the degree of inflammation in samples from abdominal aortic aneurysms." (PMID 29530068, 2018).
anemia (1 paper, 2025). A reduction in the number of red blood cells, the amount of hemoglobin, and/or the volume of packed red blood cells. "Patients in group C had a higher median age compared to group S, while group S exhibited milder anemia severity than group C. Additionally, POT1 variants were associated with the idiopathic subtype of PRCA in females, often co-occurring with STAT3 variants." (PMID 40202536, 2025).
Anxiety (1 paper, 2025). Intense feelings of nervousness, tension, or panic often arise in response to interpersonal stresses. "Moreover, brain MRI can incidentally detect benign disease that could cause unnecessary anxiety to asymptomatic individuals with POT1 variants and their families." (PMID 40350252, 2025).
bone giant cell tumour (1 paper, 2024). "Also, the relative III.30 developed a bone giant cell tumour, which despite not being a malignant tumour is clinically relevant, and was not previously associated with POT1 PV." (PMID 38839987, 2024).
breast tumors (1 paper, 2012). "First, there is a significant, negative association between telomere content and the levels of mRNA expressions of TRF2, TRF1, TIN2, and POT1 in human breast tumors." (PMID 23342266, 2012). "We demonstrate in this study that the levels of TRF2, TRF1, TIN2, and POT1 mRNA, but not TERT mRNA, are inversely correlated with telomere content (a surrogate for telomere length) in human breast tumor tissues." (PMID 23342266, 2012). "The levels of TRF2, TRF1, TIN2, and POT1 mRNA, but not telomerase reverse transcriptase (TERT) RNA, are inversely correlated with telomere content in breast tumors." (PMID 23342266, 2012). "Telomere content assays and quantitative RT-PCR demonstrate that the levels of TRF2, TRF1, TIN2, and POT1 mRNA, but not telomerase reverse transcriptase (TERT) RNA, are inversely correlated with telomere content in breast tumors." (PMID 23342266, 2012).
chronic myeloid leukemia (1 paper, 2021). "Recently, our group determined whether the BCR/ABL1 copy number, expression, and/or activity were responsible for telomere maintenance and the deregulated expression of selected shelterin components (TRF1, TRF2, RAP1, and POT1) in widely used chronic myeloid leukemia (CML) cell lines." (PMID 34885080, 2021).
desmoid tumor (1 paper, 2024). A desmoid tumor (DT) is a benign, locally invasive soft tissue tumor associated with a high recurrence rate but with no metastatic potential. "In the present study, desmoid tumors were reported in 40% of the evaluated families; a mesenteric desmoid tumor was reported recently in one POT1 carrier." (PMID 38540414, 2024).
endometrial cancer (1 paper, 2019). Primary or metastatic malignant neoplasm involving the endometrium (mucous membrane that lines the endometrial cavity). "Higher levels of point mutations in the POT1 gene were observed in endometrial cancers, revealing that genetic variations in POT1 may lead to carcinogenesis in the endometrium." (PMID 31157162, 2019). "Therefore, the loss of POT1 described in endometrial cancer may cause inappropriate telomere access of telomerase resulting in compromised telomere capping and sustained telomere dysfunction facilitating genetic instability." (PMID 31157162, 2019).
endothelial dysfunction (1 paper, 2024). In vascular diseases, endothelial dysfunction is a systemic pathological state of the endothelium (the inner lining of blood vessels) and can be broadly defined as an imbalance between vasodilating and vasoconstricting substances produced by (or acting on) the endothelium. "Moreover, depletion of POT1 has been linked to phagocytosis and nitric oxide generation, which is involved in endothelial dysfunction." (PMID 37782440, 2024).
fibrosarcoma (1 paper, 2020). A malignant mesenchymal fibroblastic neoplasm affecting the soft tissue and bone. "Successive knockdown of POT1 or overexpression of the 5’-OB fold deletion mutant form of POT1 led to telomere elongation in the telomerase-positive cell line HTC75, a cell line derived from HT1080 fibrosarcoma cells." (PMID 32687062, 2020).